NEDD4 (NEDD4 E3 ubiquitin protein ligase)
Diseases named in the same sentence as NEDD4 in open-access papers (continued):
Sharing a sentence is not in itself a finding about the gene and the disease.
tumor (continued). "Tumor volume and weight were found to be remarkably enhanced in the presence of NEDD4." (PMID 37568787, 2023). "Ubiquitin ligase NEDD4 has also been described both as an oncogene and a tumour suppressor." (PMID 38097550, 2023). "Furthermore, our group further revealed that ATT exhibits anti-cancer activity by regulating NEDD4/c-Myc/topoisomerase pathway and inhibits tumor growth in xenotransplanted tumor models." (PMID 37397487, 2023). "Furthermore, our gain and loss of functional experiments showed that a PTEN/IRS1 axis is essential for the NEDD4-targeted inhibitory effect on tumor growth in IGF1 signaling-driven GC." (PMID 36774408, 2023). "When silencing YTHDF2 and overexpressing NEDD4, the growth rate of the tumor was restored." (PMID 37605223, 2023). "Furthermore, NEDD4-overexpressing Lovo cells promoted tumor growth in mice, whereas tumor growth was reduced in mice inoculated with NEDD4-silenced-Caco-2 cells." (PMID 37568787, 2023). "In addition, the size, number and weights of tumor mass were smaller in NEDD4-/- mice as compared to wild-type mice." (PMID 37568787, 2023). "Therefore, the pharmacological targeting of NEDD4-1 and oncogenic lncRNAs will be valuable in the suppression of tumor progression." (PMID 37568787, 2023). "Additionally, an in vivo study showed that NEDD4 knockdown decreased tumor size and GSH levels, and increased MDA levels in nude mice (A375) xenografts." (PMID 36293239, 2022). "Interestingly, it is found that there are many genes upstream and downstream of NEDD4, and it has the potential to be employed as a molecular switch to control tumor development via these competitive substrates." (PMID 36293239, 2022). "Another study revealed that PRRG4-mediated recruitment of NEDD4 stimulates ubiquitination and degradation of Robo1 (a tumor suppressor gene), subsequently leading to the activation of protein tyrosine kinases Src and FAK, which are critical for BC cell motility, invasion, and metastasis." (PMID 36293239, 2022). "Moreover, knockdown of NEDD4 decreased tumor growth and tumor weight in nude mice (HCC827/ER cells) xenografts." (PMID 36293239, 2022). "In addition, in vivo findings verified that NEDD4 regulates the KLF8/miR-132/NRF2 axis by accelerating tumor growth and lung metastasis." (PMID 35031788, 2022). "NEDD4 expression is frequently increased in tumor tissues from LUAD patients." (PMID 35646490, 2022). "Importantly, it was noted that suppressing NEDD4 expression resulted in decreased cell proliferation, migration, and tumor growth." (PMID 36293239, 2022). "In another study, it was reported that depletion or inhibition of NEDD4 could be used as a strategy to minimize metastasis and postpone tumor recurrence, hence improving survival rates." (PMID 36293239, 2022). "Furthermore, a study in HeLa cells demonstrated that NEDD4 controls the level of Cx43, which acts as a tumor suppressor both at basal conditions and in response to protein kinase C activation." (PMID 36293239, 2022). "Overexpression of NEDD4 is associated with TNM stage and tumor metastasis." (PMID 35646490, 2022). "NEDD4 also exerts tumor suppressor properties in various malignancies." (PMID 36293239, 2022). "Nevertheless, several studies reported NEDD4 as a tumor suppressor." (PMID 35646490, 2022). "Furthermore, we validated this finding using the TCGA-GBM database; the results demonstrated NEDD4-1 was more highly expressed in tumor tissue than in normal tissue." (PMID 34638586, 2021). "All these elucidated the tumor suppressive role of NEDD4 in RCC carcinogenesis." (PMID 37305161, 2021). "In this study, we first found that HBV-infected HCC patients with high tumor NEDD4 expression experienced superior cumulative survival over those with low tumor NEDD4 expression and that high NEDD4 expression in HBV-positive cell lines inhibited proliferation, migration, and invasion." (PMID 33767993, 2021). "From this perspective, NEDD4 exercises a tumor suppressive function." (PMID 33767993, 2021).
tumor (continued). "We thus hypothesized that upregulated proteins by NEDD4 knockdown include tumor suppressors and potential candidates for ubiquitination targets." (PMID 33014839, 2020). "Reduced NEDD4‐1 expression was associated with increased PTEN/PI3K/Akt signaling and tumor growth." (PMID 31390487, 2020). "Whether NC attenuated tumor growth in mice via suppression of NEDD4 needs to be determined, which could be helpful for the potential use of NC in clinical trials in the future." (PMID 33288736, 2020). "Thus, the difference in NEDD4 immunoreactivity between tumor samples and adjacent tissues was significant (χ2 = 94.872, P < 0.001)." (PMID 31856858, 2019). "As tumor metastasis is a complicated multistep process, it may be that NEDD4 influences the metastatic process via some mechanism other than cell migration." (PMID 31856858, 2019). "In addition, via a comparison of the expression levels of NEDD4 with known clinicopathologic and molecular features for each patient derived from our database, we found that NEDD4 expression correlated with tumor size, nodal status, and ER and PR status." (PMID 31856858, 2019). "Notably, multiple laboratories recently identified a possible oncogenic role for NEDD4 in part by promoting the ubiquitination of the PTEN tumor suppressor to govern either its stability or its subcellular localization." (PMID 24657926, 2014). "Neuronal precursor cell-expressed developmentally down-regulated 4-1 (NEDD4-1) plays a great role in tumor cell growth, but its function and mechanism in cell invasive behavior are totally unknown." (PMID 24340059, 2013). "Furthermore, the positive rate of NEDD4-1 expression increases with tumor progression." (PMID 40535763, 2025). "However, the role of the NEDD4-PTEN axis in tumor progression remains controversial." (PMID 36774408, 2023). "Notably, NDRG1 could antagonize NEDD4-mediated ubiquitination degradation of p21 to serve as a tumor suppressor in CRC." (PMID 36831013, 2023). "Specifically, abnormal expression of NEDD4 may lead to the malignancy of tumor." (PMID 35861040, 2023). "Moreover, it was demonstrated that MCM8 may regulate the expression of CHSY1 through affecting its NEDD4-mediated ubiquitination, both of which synergistically execute tumor promotion effects on CRC." (PMID 37710286, 2023). "However, there is another line evidence supporting a tumor-suppressive role of NEDD4." (PMID 36831013, 2023). "However, the pivotal role of NEDD4 as an oncoprotein or tumour suppressor is still debated." (PMID 38097550, 2023). "Indeed, expression of NEDD4L was profoundly downregulated in CRCs, suggesting that inhibition of the tumour suppressors NEDD4/NEDD4L may be an alternative Wnt activating mechanism for some CRCs." (PMID 31867777, 2020). "Moreover, NDRG1 could emulatively antagonize NEDD4-mediated ubiquitylation of p21, increasing p21 expression and inhibit tumor proliferation." (PMID 31831018, 2019). "In summary, in addition to acetyl-CoA, our study identifies that NEDD4-dependent H3 ubiquitination is important for the rapid induction of H3 acetylation by glucose, which plays a critical role in transcriptional activation of tumour sphere factors for the maintenance of tumour sphere formation." (PMID 28300060, 2017). "Previous studies have confirmed that NEDD4 is involved in the ubiquitination and degradation of the large tumor suppressor kinase 1 (LATS1) in tumor cells, thereby affecting the activity of the Hippo pathway." (PMID 39890782, 2025). "JAC1 downregulates NEDD4-1 mRNA expression, thereby activating Smurf1-mediated proteasomal degradation of HER2 and inhibiting the proliferation of HER2-positive BC cells and tumor growth." (PMID 40535763, 2025). "Therefore, we hypothesized that NEDD4 would inhibit tumor growth in vivo." (PMID 39444619, 2024).
tumor (continued). "In NSCLC, the stability and activation of ACLY are enhanced by the dissociation between E3 ligase NEDD4 and ACLY, which promotes a high level of acetyl-CoA and fatty metabolism, subsequently inducing tumor proliferation." (PMID 37176148, 2023). "Together, our data demonstrate that suppression of USP18 promotes UBCH5 and NEDD4-mediated proteasome degradation of CSF1R, leading to an increase in anti-tumor macrophages in the TME." (PMID 38100351, 2023). "NEDD4 also promotes the resistance of NSCLC cells to erlotinib, and promotes tumor progression by negatively regulating PTEN36." (PMID 36923932, 2023). "NEDD4 intensifies the stability and transcriptional activity of KLF8 through ubiquitination and affects the miR-132/NRF2 axis, thereby promoting tumor progression." (PMID 37497216, 2023). "NEDD4 was found to be an oncogene because of its role in inhibiting PTEN, a well-known tumor suppressor." (PMID 36293239, 2022). "The expression of NEDD4 and KLF8 was elevated in tumor tissues compared to that in adjacent normal tissues." (PMID 35031788, 2022). "Genes involved in tumor neovascularization and tumor suppression such as SART3 and NEDD4, were found to be significantly differentially expressed in the loggerhead brain or gonads." (PMID 34827746, 2021). "The combination treatment of I3C, a known inhibitor of NEDD4-1, with TMZ resulted in a synergistic effect and re-sensitized TMZ-resistant tumor cells both in vitro and in vivo." (PMID 34638586, 2021). "In this study, we compared NEDD4 expression between HBV-positive and HBV-negative HCC tumor tissues." (PMID 33767993, 2021). "Unlike the previous report showing that Nedd4‐deficient tumour phenotype requires surrounding microenvironment, our results show that deletion of Nedd4/Nedd4l in the intestinal epithelium alone is sufficient to enhance Apcmin tumour growth with significant increase in ISC numbers." (PMID 31867777, 2020). "Here, we investigate the role of NEDD4 and NEDD4L in the context of intestinal homeostasis and tumour development." (PMID 31867777, 2020). "In conclusion, our work shows that NEDD4 and NEDD4L are crypt‐expressing tumour suppressors by targeting the RSPO receptor LGR5 and DVL2 for degradation." (PMID 31867777, 2020). "Meanwhile NEDD4–1 can regulate Ras-GDP level of all three forms and subsequently drives PTEN degradation, leading to tumor processes." (PMID 31988639, 2020). "Functionally, we show that NEDD4-mediated H3 ubiquitination, by transcriptionally activating IL1α, IL1β and GCLM, is important for tumour sphere formation." (PMID 28300060, 2017). "More importantly, dysregulated NEDD4 degradation led to reduction in PTEN expression and subsequent hyper-activation of the oncogenic mTOR/Akt pathway, resulting in enhanced tumor cell proliferation and growth." (PMID 24657926, 2014). "Our study found that NEDD4 mediated the ubiquitination and degradation of PTEN by binding to PTEN, which activated the downstream PI3K/Akt/mTOR signaling pathway, thus promoting OXA and 5-Fu resistance in tumor cells." (PMID 39890782, 2025). "For instance, NEDD4 has been shown to function as a tumor promoter in colorectal cancer, highlighting the complexity of its role in tumorigenesis; whereas, NEDD4L functions as a tumor suppressor by controlling Wnt signaling pathway." (PMID 41385185, 2025). "NEDD4 knockdown weakened A549CSC and H1975CSC tumor sphere formation (size and number)." (PMID 39444619, 2024). "Furthermore, knockout of NEDD4 in CRC cells reduced proliferation, colony-forming abilities and tumour growth in mice." (PMID 38097550, 2023). "Moreover, we also established the xenograft tumor model in nude mice using NEDD4-overexpressing BGC803 cells and monitored the tumor volumes and measured the tumor weights." (PMID 36774408, 2023). "Furthermore, NEDD4 depletion in CRC cells reduced proliferation, colony-forming abilities and tumour growth in mice." (PMID 38097550, 2023).
tumor (continued). "Mice bearing NEDD4 KO tumour, though small, exhibited no reduction in tumour burden upon 5-FU treatment." (PMID 38097550, 2023). "NEDD4 induces p-AKT K48-linked ubiquitination, resulting in its degradation, and depletion of NEDD4 in MM cells resulted in decreased drug sensitivity by elevating p-AKT, thereby indicating that NEDD4 may also have a tumor suppressive role." (PMID 37176148, 2023). "It was established that NEDD4 KO did not cause tumour growth sporadically, however, when NEDD4 KO mice were crossed with sporadic CRC models, the tumour burden was significantly accelerated." (PMID 38097550, 2023). "In addition, NEDD4 knockdown along with NRG-1 and HER3 mAb in an MCF-7 (shNEDD4) mice xenograft showed decreased tumor volume." (PMID 36293239, 2022). "Moreover, inactivation of NEDD4 and NEDD4L promotes Wnt activation, which improves tumor propensity and progression." (PMID 36293239, 2022). "Indeed, the inactivation of NEDD4/NEDD4L induces Wnt activation and intestinal stem cells numbers, inducing tumor progression." (PMID 35205738, 2022). "Identification of NEDD4 as an E3 ubiquitin ligase involved in the regulation of availability IGPR-1 at the cell surface represents a key mechanism with major implications in cell–cell adhesion, mechanosensing and tumor promoting activity of IGPR-1." (PMID 33962630, 2021). "Importantly, the mechanistic biomarkers including JWA, p-p38, GATA-1, NEDD4, and SMURF1 were correspondingly changed in tumor tissues." (PMID 33875644, 2021). "Therefore, we first investigated the correlation between NEDD4 expression and HBV exposure through analyzing tumor samples from 104 patients with HBV-positive HCC and 95 patients with HBV-negative HCC using qRT-PCR." (PMID 33767993, 2021). "Because NEDD4 acts as a tumor promoter in NSCLC, inactivation of NEDD4 might be a potential treatment for NSCLC patients." (PMID 33288736, 2020). "NEDD4, also known as neural precursor cell expressed developmentally downregulated protein 4, has been reported as E3 ligase for many substrates, including EGFR, PTEN, and ERBB4, and it was involved in tumor and other diseases." (PMID 31831018, 2019). "Interestingly, we also found that H3 ubiquitination, together with NEDD4, GCN5 and histone H3.3, are novel regulators for tumour sphere formation." (PMID 28300060, 2017). "Moreover, we found that NEDD4 promotes proliferation and tumor formation of GC cells sensitive to IGF1R inhibitor but not the insensitive ones in a PTEN-dependent manner." (PMID 36774408, 2023). "However, by promoting the expression of the c-Myc E3 ligase neural precursor cell expressed developmentally downregulated gene 4 (NEDD4), artemisitene (ATT) treatment destabilized c-Myc in tumor cells and damaged the DNA of tumor cells, thus playing an anti-tumor role." (PMID 34407830, 2021). "In addition, NEDD4 expression showed no obvious relationship with other well-known clinicopathological variables, such as age, menstruation status, tumor grades, Her2 status, or Ki-67 status (P > 0.05, respectively)." (PMID 31856858, 2019). "Thus, it is unlikely to be that our finding showing NEDD4 regulates H3 acetylation and tumour sphere is through AKT signalling pathway." (PMID 28300060, 2017). "Interestingly, we also found that the treatment of IL1β could not fully rescue the defect in tumour sphere formation upon NEDD4 knockdown, despite that IL1β alone readily increased the tumour sphere numbers in control cells, indicating that there are other important factors involved." (PMID 28300060, 2017). "Unlike NEDD4, NEDD4L exhibits more complex roles in tumor progression." (PMID 35646490, 2022). "As a result, unlike NEDD4-1 or WWP2, FBXO22 did not affect AKT activation, but negatively regulated nuclear PTEN functions, such as the activity of APC/C-CDH1 complex and alternative splicing, to play a tumor-promoting role." (PMID 32249768, 2020).
tumor (continued). "Knockdown of NEDD4 diminished both the EGF- and the non-EGF-dependent cell migration capacity evaluated by penetration of micro-pores of the membrane in the transwell, which resembles the escaping process of tumor cells from tumor tissues into blood stream." (PMID 29455656, 2018). "Taken together, these results suggest that by evading β-TRCP-mediated degradation, cells expressing the non-degradable version of NEDD4 (NEDD4-AA) have increased cell growth and cell migration, presumably through the activated mTOR/Akt pathway by suppressing the PTEN tumor suppressor." (PMID 24657926, 2014).